GPR6 (G protein-coupled receptor 6)
Description:
Constitutively active G protein-coupled receptor that maintains high cAMP levels and contributes to several processes including neuronal development, through activation of intracellular signaling pathways via G(s). May be activated by lipid-derived agonists such as oleic acid or sphingosine 1-phosphate, leading to activation of the G(s)/cAMP/PKA signaling pathway.
Tractability: Small molecule: a structure with a bound ligand is known; a high-quality ligand is known; it belongs to a druggable protein family. Antibody: UniProt places it where antibodies can reach, with high confidence; its Gene Ontology location is reachable by antibodies, with high confidence; UniProt predicts a signal peptide or a membrane-spanning region. PROTAC: a small molecule that binds it is known.
Target class: Family A G protein-coupled receptor; Membrane receptor
Gene: Protein-coding gene on chromosome 6 (109,978,256 to 109,980,720, forward strand). Ensembl gene ENSG00000146360.
Subcellular location: Cell membrane
Gene Ontology:
Molecular function: protein binding; G protein-coupled receptor activity; sphingosine-1-phosphate receptor activity
Biological process: adenylate cyclase-activating G protein-coupled receptor signaling pathway; G protein-coupled receptor signaling pathway; sphingosine-1-phosphate receptor signaling pathway
Cellular component: cytoplasm; plasma membrane; membrane
Genetic constraint (gnomAD): Loss-of-function variants: 14 observed, 19.24 expected, observed/expected ratio (o/e) 0.73, 90% interval 0.48 to 1.14. The synonymous counts are far from expectation, so gnomAD's model fits this gene poorly and the ratio says little. Missense variants: 477 observed, 489.13 expected, observed/expected ratio (o/e) 0.98, 90% interval 0.9 to 1.05. Synonymous variants: 299 observed, 243.85 expected, observed/expected ratio (o/e) 1.23, 90% interval 1.12 to 1.35.
Homologues: Orthologues: chimpanzee GPR6 (100% identical), macaque GPR6 (99% identical), rabbit GPR6 (96% identical), dog GPR6 (94% identical), mouse Gpr6 (94% identical), rat Gpr6 (94% identical), tropical clawed frog gpr6 (63% identical), zebrafish gpr6 (62% identical). Paralogues in human: GPR12 (52% identical), GPR3 (52% identical), S1PR5 (27% identical), LPAR2 (25% identical), S1PR2 (25% identical), CNR1 (24% identical), CNR2 (24% identical), S1PR1 (24% identical), S1PR3 (23% identical), LPAR3 (23% identical), MC1R (23% identical), MC3R (23% identical), and 6 more.
Diseases named in the same sentence as GPR6 in open-access papers:
GPR6 is named in the same sentence as 11 diseases in open-access papers, as found by Europe PMC text mining. Sharing a sentence is not in itself a finding about the gene and the disease. The quoted sentences say what the papers report.
Parkinson disease (8 papers, 2015 to 2025). A progressive degenerative disorder of the central nervous system characterized by loss of dopamine producing neurons in the substantia nigra and the presence of Lewy bodies in the substantia nigra and locus coeruleus. "This process is inherently dependent on the researchers’ interests, so we focused on Drd1 and Gpr6, which are implicated in Parkinson’s disease (PD) due to their hypo- and hyperactivity, respectively." (PMID 39345494, 2025). "We focused on Drd1 and Gpr6, which are implicated in Parkinson’s disease (PD) due to their hypo- and hyperactivity, respectively." (PMID 41163012, 2025). "Highlighting cross-expression’s biological utility, our network shows that genes Drd1 and Gpr6, which are individually implicated in Parkinson’s disease (PD) and are being pursued as therapeutic targets, are cross-expressed within the striatum, hinting at their joint role in PD pathophysiology." (PMID 39345494, 2025). "GPR6 is implicated in Parkinson’s disease, Alzheimer’s disease, and neuronal cell survival." (PMID 33801713, 2021). "Our findings are in part consistent with those findings in mammals where GPR6 is mainly located in the striatum and hypothalamus and participates in neurite outgrowth, thus being related with Alzheimer’s disease, Parkinson’s disease, and instrumental learning." (PMID 33801713, 2021). "In fact, several patents claim the use of pyrazine derivatives as GPR6 inverse agonists for treating Parkinson’s disease symptoms and other dyskinesia syndromes." (PMID 32046081, 2020). "In fact, diverse research groups have demonstrated that GPR6 represents a possible target for the treatment of neurodegenerative disorders such as Parkinson’s disease, Alzheimer’s disease, and Huntington’s disease." (PMID 32046081, 2020). "Diminishing the constitutive signaling of GPR6 is currently being pursued by the pharmaceutical industry as a therapeutic approach for the management of Parkinson’s disease." (PMID 32046081, 2020). "Knocking out GPR6 in a Parkinson’s disease mice model results in a decrease of the involuntary movements that characterize this disease." (PMID 32046081, 2020). "Several patents have claimed the use of a wide range of pyrazine derivatives as GPR6 inverse agonists for the treatment of Parkinson’s disease symptoms and other dyskinesia syndromes." (PMID 32046081, 2020). "GPR6 has been suggested as a possible target for the treatment of Parkinson’s disease." (PMID 32046081, 2020). "They reduce dyskinesia after apomorphine and quinpirole treatment in a mouse model of Parkinson’s disease, suggesting that the GPR6 inhibition may lead to improvement of Parkinson’s disease." (PMID 26101869, 2015). "Gpr6 is an adenylate cyclase-activating GPCR (Gs) with CBD as an inverse agonist and has been proposed as a therapeutic target of AD and Parkinson's disease." (PMID 40979532, 2025). "The discovery that GPR3, GPR6, and GPR12 are molecular targets for CBD provided important mechanistic insight for understanding the therapeutic potential of CBD for various diseases, including Alzheimer’s disease and Parkinson’s disease." (PMID 39404382, 2024). "GPR3, GPR6, and GPR12 are expressed in various areas of the brain and peripheral tissues, where they play important roles in pathological conditions such as Alzheimer’s disease, Parkinson’s disease, addiction, obesity, and cancer." (PMID 39404382, 2024).
Alzheimer disease (4 papers, 2020 to 2024). A progressive, neurodegenerative disease characterized by loss of function and death of nerve cells in several areas of the brain leading to loss of cognitive function such as memory and language. "GPR6 is involved in other neurological disorders such as Huntington’s and Alzheimer’s Disease." (PMID 32046081, 2020). "S1P, as an agonist on GPR3, GPR6, GPR12, may be a promising target in Alzheimer’s Disease." (PMID 38895631, 2024).
Anxiety (2 papers, 2022 to 2023). Intense feelings of nervousness, tension, or panic often arise in response to interpersonal stresses. "There are several orphan GPCRs, such as GPR88, GPR101, GPR52, and GPR6, which display a robust striatal expression and have been associated to anxiety and/or depressive-like states." (PMID 33589739, 2022). "Even though there are no studies about GPR6 effects on anxiety or depression-like behaviors, this GPCR is another possible MDD drug target." (PMID 33589739, 2022).
Dyskinesia (1 paper, 2024). A movement disorder which consists of effects including diminished voluntary movements and the presence of involuntary movements. "For example, researchers found that the deletion of GPR6 in mice leads to a decrease in striatal cAMP levels, an increase in locomotor activity, and slight reductions in L-DOPA or dopamine agonist-induced dyskinesia." (PMID 38882525, 2024).
ischaemic stroke (1 paper, 2021). "Previously, we identified the human orthologues for a number of rat genes, which expression was changed after ischaemic stroke (Adora2a, Bcl3, Ccl22, Ccr1, Cd14, Gpr6, Gpr88, Rgs9, and other genes)." (PMID 34946819, 2021).
Obesity (1 paper, 2018). Accumulation of substantial excess body fat. "Interestingly, GPR6 knockout mice exhibit hyperphagia-induced obesity and higher liver triglyceride content, plasma insulin, and leptin levels compared to wild-type mice." (PMID 30564199, 2018).
nervous system diseases (2 papers, 2021 to 2023). "The mRNAs of Rgs9, Gpr88, Drd2, Sh3rf2, Tac1, Serpina 9, Rxrg, Drd1, Rasgrp2, Six3, Gpr6, Pdyn, Gng7, and Pde1b were all upregulated (p < 0.05); all of these have been reported to be more or less related to nervous system diseases." (PMID 33819195, 2021).
neurodegenerative disease (2 papers, 2020 to 2024). A disorder of the central nervous system characterized by gradual and progressive loss of neural tissue and neurologic function. "Molecules targeting GPR3, GPR6 and GPR12 are of interest for therapeutic applications since they are implicated in several neurodegenerative diseases, including AD, PD, HD and MS." (PMID 38895631, 2024). "The high abundance of GPR6 in the central nervous system, along with high constitutive activity and a link to several neurodegenerative diseases make GPR6 a promising biological target." (PMID 32046081, 2020). "Despite the promising roles of GPR3, GPR6, and GPR12 in neurodegenerative diseases, including AD, further research is required to fully elucidate their mechanisms of action and validate them as viable therapeutic targets." (PMID 38895631, 2024).
tumor (1 paper, 2022). "From our findings, three (GPR6, GRASP, JDP2) of the six validated genes of phase A are related to EMT and tumor migration; one validated gene (GNPDA1) links to the glycolytic pathway and glycosylation." (PMID 35563509, 2022).
GPR6 also shares sentences with these, for which no sentence is quoted: diabetes (1 paper); Huntington disease (1).